NGF (nerve growth factor)
Diseases named in the same sentence as NGF in open-access papers (continued):
Sharing a sentence is not in itself a finding about the gene and the disease.
muscular dystrophy (2 papers, 2019 to 2024). Muscular dystrophy (MD) refers to a group of more than 30 genetic diseases characterized by progressive weakness and degeneration of the skeletal muscles that control movement. "The loss of the neurotrophin NGF has been linked to muscular dystrophy." (PMID 30875922, 2019).
myeloid leukaemia (2 papers, 2017 to 2024). "Consistent with TRKB activation, transplantation of TRKA and NGF modified 32D cells (murine myeloid progenitors) induced only myeloid leukemia in C3H/HeJ animals without any sign of increased mastocyte numbers." (PMID 29088753, 2017).
neuro-degenerative diseases (2 papers, 2018 to 2025). "NGF neurotrophin can improve remyelination by promoting myelin repair in animal models of neuro-degenerative diseases, and has been shown to be critical for survival; the axonal growth of neurons also affects the regulation of proliferation, differentiation, neuro-transmission, and plasticity." (PMID 28975357, 2018). "Neurotrophins, including nerve growth factor (NGF) and brain-derived neurotrophic factor (BDNF), were studied to assess the possibility of preventing retinal neurodegeneration in DR and, consequently, to avert retinal vascular damage." (PMID 40564047, 2025).
neurodegenerative diseases of the eye (2 papers, 2019 to 2020). "The pleiotropic NGF effects have been described either in vitro (cell culture models) or in vivo (experimental models and humans), leading to the development of clinical trials devoted to demonstrating the useful NGF administration in neurodegenerative eye diseases." (PMID 33584278, 2020).
ocular cicatricial pemphigoid (2 papers, 2015 to 2025). Ocular cicatricial pemphigoid (OCP) is a form of mucous membrane pemphigoid (a group of rare, chronic autoimmune disorders) that affects the eyes. "In a previous study, we reported the upregulation of Nerve Growth Factor (NGF) and trkANGFR expression in Ocular Cicatricial Pemphigoid (OCP), an inflammatory and remodeling eye disease." (PMID 26569118, 2015).
oral mucositis (2 papers, 2017 to 2024). Inflammation of the mucous membranes of any of the structures in the mouth. "Given the good results obtained by the application of NGF on skin conditions, topical application of NGF could be tried out as a treatment for oral mucositis, recurrent oral aphthous ulcers and bisphosphonate-associated osteonecrosis of the jaw." (PMID 28208669, 2017). "In the oral cavity, no studies have so far been carried out to examine whether NGF could be used in chronic mucosal ulcerations or wounds, such as oral mucositis, recurrent oral aphthous ulcers and bisphosphonate-associated osteonecrosis of the jaw." (PMID 28208669, 2017).
Ovarian Failure (2 papers, 2019 to 2020). "The data of this experiment show that exogenous NGF can improve the ovarian dysfunction caused by CUMS." (PMID 32685448, 2020). "UCMSCs could reduce ovarian failure due to premature senescence caused by chemotherapy, and the NGF/TrkA signaling pathway was involved in the amelioration of POF." (PMID 31240219, 2019). "Therefore, UCMSCs could reduce ovarian failure due to premature senescence caused by chemotherapy, and the NGF/TrkA signaling pathway was involved in the amelioration of POF." (PMID 31240219, 2019). "The mechanisms underlying ovarian dysfunction and POI caused by chronic stress remain unclear and may be associated with NGF." (PMID 32685448, 2020).
peripheral arterial disease (2 papers, 2019 to 2024). A disorder of the arteries supplying the upper and lower extremity and the visceral organs. "Recently, several studies from Li and colleagues highlighted the importance of increased NGF in lumbar DRGs to the genesis of the exaggerated EPR by affecting the metaboreflex in peripheral arterial disease." (PMID 30909643, 2019).
pneumococcal meningitis (2 papers, 2017 to 2020). An acute purulent infection of the meninges and subarachnoid space caused by Streptococcus pneumoniae, most prevalent in children and adults over the age of 60. "Among those drugs, we studied the effect of tamoxifen as well as lithium on BDNF, GDNF, and NGF expression in the hippocampus and on behavior tasks in an experimental model of pneumococcal meningitis in rats." (PMID 29200666, 2017). "Hence, the aim of this study was to investigate the effects of lithium and tamoxifen on BDNF, GDNF, and NGF expression in the hippocampus and on behavior tasks in an experimental model of pneumococcal meningitis." (PMID 29200666, 2017). "In our experiment, we observed that lithium prevented memory impairment and increased hippocampal BDNF, NGF, and GDNF neurotrophin expression in experimental pneumococcal meningitis." (PMID 29200666, 2017). "The aim of this study was to investigate the effects of lithium on brain-derived neurotrophic factor (BDNF), nerve growth factor (NGF), and glial cell line-derived neurotrophic factor (GDNF) expression in the hippocampus and on memory in experimental pneumococcal meningitis." (PMID 29200666, 2017).
prion disease (2 papers, 2017 to 2024). A transmissible disease that is caused by a protein that is able to induce abnormal folding of normal cellular proteins, leading to characteristic spongiform brain changes, which are associated with neuronal loss without an inflammatory response. "Invariable expression of tropomyosin-related kinase A (TrkA) and sortilin, the co-receptors of p75NTR for cell survival and death respectively, suggest their insignificant role in prion disease, so also with proNGF/NGF, the genuine ligand of p75NTR." (PMID 38802941, 2024).
proliferative diabetic retinopathy (2 papers, 2013 to 2021). Advanced retinopathy due to diabetes mellitus characterized by the formation of new vessels in the retina. "We investigated the expression of the NTs nerve growth factor (NGF), brain-derived neurotrophic factor (BDNF), neurotrophin-3 (NT-3), and neurotrophin-4 (NT-4) and their receptors TrkA, TrkB, and TrkC in proliferative diabetic retinopathy (PDR)." (PMID 23762379, 2013). "In addition, NGF in tears exhibited a higher level in patients with proliferative diabetic retinopathy than that in non-diabetic controls and non-proliferative diabetic retinopathy patients; that parameter is promising to evaluate the status of DR." (PMID 34876936, 2021).
psoriasis vulgaris (2 papers, 2012). Plaque psoriasis is the most common presentation of psoriasis. "A bigger pool of samples could be used in future to look at the association of NGF with psoriasis vulgaris and to research further on the angiogenesis pathways of NGF on psoriasis vulgaris." (PMID 22537619, 2012). "Therefore, would a new targeted therapy for the NGF be the future research area for psoriasis vulgaris?" (PMID 22537619, 2012). "The comparative levels of immunohistochemistry expression of the VEGF (subfamily A, B, C, D and PlGF), NGF and vWFr in psoriasis vulgaris are still unknown." (PMID 22537619, 2012). "In conclusion, this study involved a small sample size and showed a significant finding on the contribution of the NGF and the VEGF-C in the pathogenesis of psoriasis vulgaris." (PMID 22537619, 2012). "The newly discovered angiogenesis growth factors’ (NGF and vWFr) expression in psoriasis vulgaris in comparison with the VEGF family has never been documented." (PMID 22537619, 2012). "The NGF (angiogenesis) and VEGF-C (lymphangiogenesis) might play a crucial role in the pathogenesis of psoriasis vulgaris and could be researched further as potential new targeted therapies for psoriasis vulgaris." (PMID 22537619, 2012).
pterygium (2 papers, 2022 to 2025). A wedge-shaped fibrovascular lesion arising from the bulbar conjunctiva and extending to the cornea. "The study proposed that NGF is present and activates TrkANGFR in pterygium, suggesting its involvement in the angiogenic response characteristic of this condition." (PMID 40649793, 2025).
radiculopathy (2 papers, 2025). Disease involving a spinal nerve root (see spinal nerve roots) which may result from compression related to intervertebral disk displacement; spinal cord injuries; spinal diseases; and other conditions. "A study17tested two biological agent classes: anti-TNFs for patients with chronic LBP with radiculopathy and anti-nerve growth factor (NGF) for chronic non-radicular LBP." (PMID 41195355, 2025). "Presently, the routine use of TNF or NGF inhibitors is not supported in radiculopathy or chronic LBP." (PMID 41304859, 2025).
respiratory infections (2 papers, 2009 to 2014). "Thus, pharmacologic modulation of NGF expression may offer a promising new approach for management of common respiratory infections." (PMID 19649262, 2009). "The concentrations used to generate these NGF concentration–response curves are clinically relevant and reflect levels found in both the blood and BAL‐fluid samples of infants experiencing respiratory infections and after surgery." (PMID 25347857, 2014).
retinal detachment (2 papers, 2009 to 2022). An eye emergency condition which may lead to blindness if left untreated. "A similar anti-apoptotic effect of exogenous NGF has also been described in experimental retinal detachment." (PMID 19473529, 2009). "In line with this hypothesis, it has been shown that exogenous NGF protects retinal cells from degeneration and apoptosis in experimental retinal detachment and in models of RP." (PMID 35330834, 2022).
retinal ischemia (2 papers, 2018 to 2020). A ischemic disease that involves the retina. "Retinal ischemia and the subsequent secretion of angiogenic factors including VEGF and NGF are thought to be common precursors to retinal neovascularization." (PMID 30131506, 2018).
schwannomatosis (2 papers, 2015 to 2021). The least frequent form of the rare genetic disorder neurofibromatosis. "As pain is the major symptom experienced by patients with schwannomatosis, the anti-nerve growth factor (NGF) neutralizing monoclonal antibody tanezumab is being tested in a phase 2 trial for pain alleviation (ClinicalTrials.gov Identifier: NCT04163419)." (PMID 34604034, 2021). "The schwannomatosis cells also expressed the Schwann cell markers, p75NTR, S100B, and NGF after multiple passages." (PMID 26657314, 2015).
Sciatica (2 papers, 2021 to 2023). Pain in the lower back and hip radiating in the distribution of the sciatic nerve. "Preclinical studies have demonstrated that levels of NGF are elevated in a variety of chronic pain conditions (eg, interstitial cystitis, prostatitis, arthritis, pancreatitis, chronic headaches, cancer pain, diabetic neuropathy, sciatica, and other noncancer pain)." (PMID 33480861, 2021). "This systematic review and meta-analysis will assess the evidence for the efficacy and safety of NGF inhibitors for pain in patients with nonspecific LBP and sciatica." (PMID 33480861, 2021). "This systematic review with meta-analysis will assess the evidence for the efficacy and safety of NGF inhibitors for pain in patients with nonspecific LBP and sciatica." (PMID 33480861, 2021).
sensorineural hearing loss (2 papers, 2023). "Patients with sensorineural hearing loss have been found to have low levels of NGF in their serum." (PMID 37049613, 2023).
steatosis (2 papers, 2024). Increased lipid within the cytoplasm of cells. "Additional studies have demonstrated that liver proteins are targeted for degradation following liver injury/steatosis, including nerve growth factor as well as the CASP8 and FADD-like apoptosis regulator." (PMID 38237682, 2024).
stress-related disorder (2 papers, 2020 to 2021). Stress-related disorders are mental health disorders that are a result of an atypical response to both short and long-term anxiety due to physical, mental, or emotional stress. "BDNF, GDNF, and NGF are the most abundant neurotrophins that existed in CNS and involved in the pathophysiology of mood and other stress-related disorders (Bjorkholm & Monteggia 2016, Castren & Kojima 2017, von Bohlen Und Halbach & von Bohlen Und Halbach 2018)." (PMID 34605773, 2021).
tauopathies (2 papers, 2008 to 2023). "On the other hand, the involvement of NGF system in tauopathies should be deeply investigated in order to better understand the molecular mechanism of the FTD pathogenesis." (PMID 38332808, 2023). "The interaction between NGF and Tau in AD or tauopathies is less clear: NGF-induced neuronal differentiation of the neuroblastoma cell line pheochromocytoma celline-12 (PC-12) exhibits an increase in Tau promoter activity and subsequently elevated Tau protein levels." (PMID 18184369, 2008).
Thiamine deficiency (2 papers, 2018 to 2020). Thiamine deficiency is a condition that occurs due to not enough thiamine (vitamin B1). "Exercise has been shown to increase both BDNF and NGF levels in the hippocampus in normal rats, and exercise recovers BDNF and NGF neurotrophin deficits in rats made amnestic by thiamine deficiency." (PMID 30443202, 2018). "We determined that exercise-induced changes in NGF are critical for restoring waning cholinergic/nestin neurons, blunted hippocampal ACh efflux and impaired spatial behavior following thiamine deficiency." (PMID 30443202, 2018).
triple-negative breast carcinoma (2 papers, 2021 to 2022). An invasive breast carcinoma which is negative for expression of estrogen receptor (ER), progesterone receptor (PR), and human epidermal growth factor receptor 2 (HER2). "The present data support the key role of the nerve growth factor/tropomyosin receptor kinase A pathway in triple-negative breast cancer and offer new hints in the diagnostic and therapeutic management of patients." (PMID 34268306, 2021). "Activation of tropomyosin receptor kinase by nerve growth factor treatment positively affects the migration, invasion, and proliferation of triple-negative breast cancer cells." (PMID 34268306, 2021). "Many solid tumors exhibit derangements of the nerve growth factor and its receptors, including the tropomyosin receptor kinase A. This receptor is expressed in triple-negative breast cancer, although its role in the pathogenesis and aggressiveness of this disease is still under investigation." (PMID 34268306, 2021). "We now report that triple-negative breast cancer-derived MDA-MB-231 and MDA-MB-453 cells express appreciable levels of tropomyosin receptor kinase A and release a biologically active nerve growth factor." (PMID 34268306, 2021).
ventricular tachycardia (2 papers, 2008 to 2022). A disorder characterized by an electrocardiographic finding of three or more consecutive complexes of ventricular origin with a rate greater than a certain threshold (100 or 120 beats per minute are commonly used). "The study confirmed that RDN can reduce the occurrence of ventricular tachycardia in AMI rats, reduce renal sympathetic nerve discharge, and inhibit the activity of local sympathetic nerves and cell growth factor (NGF) protein expression in the heart after AMI." (PMID 36510123, 2022).
acanthamoebiasis (1 paper, 2022). "It is possible that the upregulation of NGF in an immunocompromised host (AS) in this study is related to T-cell activation during acanthamoebiasis." (PMID 35563321, 2022). "We also showed a significant involvement of nerve growth factor in acanthamoebiasis in immunosuppressed hosts." (PMID 35563321, 2022). "During acanthamoebiasis, we observed probably the pro-inflammatory action of NGF, particularly in the immunocompromised hosts (AS)." (PMID 35563321, 2022). "In immunosuppressed hosts, we noted a probable pro-inflammatory effect of NGF during acanthamoebiasis." (PMID 35563321, 2022). "We also observed a pro-inflammatory effect of NGF during acanthamoebiasis in immunosuppressed hosts." (PMID 35563321, 2022). "Thus, to clarify the role of NT in the cerebral cortex and hippocampus during acanthamoebiasis in relation to the host immune status, the purpose of this study was to determine how brain acanthamoebiasis affects the concentrations of the neurotrophins BDNF, NGF, NT-3, and NT-4." (PMID 35563321, 2022).
acne (1 paper, 2009). An inflammatory process of the sebaceous glands which is characterized by comedones, nodules, papules and/or pustules on the skin. "The increase in nerve fibres in acne-prone skin may result from raised expression of nerve growth factor on the sebaceous glands which act as a neurotrophic molecule stimulating the sprouting of nerve fibres in the skin." (PMID 19758425, 2009).
acute leukemia (1 paper, 2017). A clonal (malignant) hematopoietic disorder with an acute onset, affecting the bone marrow and the peripheral blood. "In the TRKA/NGF group, four animals developed acute leukemia within 6 months after transplantation, while three animals developed SM within 12 months after transplantation." (PMID 29088753, 2017).
adenoma (1 paper, 2025). A neoplasm arising from the epithelium. "Transdifferentiation theory: suggests that neuronal differentiation of preexisting adenoma cells is mediated via nerve growth factor (NGF) and its receptor NGFR, which have been detected in some adenoma subtypes." (PMID 41346449, 2025).
age-related hearing impairment (1 paper, 2023). "Taken together, these results confirm that the NGF performs significant protective efficacy on age-related hearing impairment by ameliorating hearing performances and preserving histopathology of the cochlea in the preclinical model of accelerated senescence SAMP8." (PMID 37704645, 2023).
AIDS (1 paper, 2014). A syndrome resulting from the acquired deficiency of cellular immunity caused by the human immunodeficiency virus (HIV). "The ability of HERV-K(II) Env to mediate activation of the neurotrophins, BDNF and NGF, which are altered in HIV/AIDS implies HERV overexpression might have an intrinsic adaptive function by reducing the brain’s susceptibility to neuronal injury." (PMID 24988390, 2014).
Airway obstruction (1 paper, 2006). Obstruction of conducting airways of the lung. "In this respect, it is interesting to note that while both NGF and BDNF have been shown to evoke airway hyperreactivity in animal studies, they may have distinct roles in allergen-dependent airway obstruction." (PMID 16441896, 2006).
anti-phospholipid syndrome (1 paper, 2013). "Although numbers of NGF-producing cells were independent of clinical SLE profiles, CD19+ BDNF-producing B cells were dramatically decreased in patients with an associated anti-phospholipid syndrome (40.2 ± 8.9 vs 80.5 ± 22.05, p=0.03)." (PMID 24223945, 2013).
Ataxia (1 paper, 2025). Ataxia refers to impaired coordination of voluntary muscle movement. "NGF may cause central nervous system side effects such as ataxia, sensory abnormalities, and even accelerated side effects such as structural deterioration of joints." (PMID 40860871, 2025). "NGF may also cause side effects such as ataxia, sensory abnormalities, and even accelerated joint deterioration." (PMID 40860871, 2025).
auditory neuropathy (1 paper, 2022). A hearing disorder characterized by impaired transmission of signals through the auditory nerve, resulting in mild to severe hearing loss and poor speech perception. "Neurotrophic factors such as BDNF, CNTF, NT3, and NGF have been tested in animal models of auditory neuropathy in different studies." (PMID 35720065, 2022).
autonomic disease (1 paper, 2024). "NGF synthesis is inhibited in the epidermis of diabetic mice, and NGF supplementation exacerbates neuropathic alterations in small fibers and autonomic disease." (PMID 39061964, 2024).
axonal sensory neuropathy (1 paper, 2021). "In contrast, thalidomide may cause axonal sensory neuropathy through the depletion of nerve growth factor (NGF)." (PMID 33805565, 2021).
B-cell lymphoma (1 paper, 2017). "Candidate antibodies for treatment of canine B-cell lymphoma and “caninized” anti-nerve growth factor (NGF) have been reported in veterinary medicine." (PMID 28983085, 2017).